MIR3133 (microRNA 3133)
Synonyms: hsa-mir-3133
Gene: MicroRNA gene on chromosome 2 (241,477,905 to 241,477,982, forward strand). Ensembl gene ENSG00000263752.
Homologues: Orthologues: chimpanzee MIR3133 (100% identical).